IGSF10 (immunoglobulin superfamily member 10)
Diseases named in the same sentence as IGSF10 in open-access papers (continued):
Sharing a sentence is not in itself a finding about the gene and the disease.
Delayed puberty (2 papers, 2020 to 2021). Passing the age when puberty normally occurs with no physical or hormonal signs of the onset of puberty. "However, recently, next-generation sequencing analysis has led to the discovery of new genes (i.e., IGSF10, HS6ST1, FTO, and EAP1) that are implicated in determining isolated self-limited delayed puberty in some families." (PMID 32508745, 2020).
esophageal cancer (2 papers, 2017 to 2022). A primary or metastatic malignant neoplasm involving the esophagus. "The Cholangiocarcinoma (CHOL), Esophageal carcinoma (ESCA), Pancreatic adenocarcinoma (PAAD) and Rectum adenocarcinoma (READ) cohorts had similar IGSF10 expression in contrast to paired normal specimens." (PMID 36685968, 2022).
glioma (2 papers, 2021). A benign or malignant brain and spinal cord tumor that arises from glial cells (astrocytes, oligodendrocytes, ependymal cells). "Kaplan-Meier survival analysis showed that IGSF10 expression was inversely correlated with survival outcomes of kidney chromophobe (KICH), sarcoma (SARC), lower grade glioma (LGG), uterine corpus endometrial carcinoma (UCEC), thymoma (THYM), and LUAD patients." (PMID 34351868, 2021).
head and neck cancer (2 papers, 2023 to 2025). A primary or metastatic malignant neoplasm affecting the head and neck. "IGSF10, a member of the immunoglobulin superfamily, is expressed at low levels in various cancers, including lung, breast, colon, and head and neck cancers." (PMID 40598621, 2025). "ELF5 and IGSF10 mRNA levels are significantly decreased in human head and neck cancers." (PMID 36820942, 2023).
osteosarcoma (2 papers, 2016 to 2022). A usually aggressive malignant bone-forming mesenchymal neoplasm, predominantly affecting adolescents and young adults. "Previous study reported that significantly reduced expression of IGSF10 was detected in a radiation-induced rat osteosarcoma model." (PMID 36685968, 2022). "Our outcomes confirmed that IGSF10 expression were drastically associated with OS in BLCA, BRCA, LUAD, KICH, LAML, LGG, CESC, Osteosarcoma (OS), SARC, STAD, THCA, and UCEC." (PMID 36685968, 2022). "On the basis of our results, we found that IGSF10 played a beneficial role in five tumors including BRCA, LUAD, LUSC, Osteosarcoma (OS) and TGCT." (PMID 36685968, 2022).
pancreatic adenocarcinoma (2 papers, 2021 to 2022). "The highest correlation between IGSF10 expression and immunoscore was observed in pancreatic adenocarcinoma (PAAD) (R=0.539, P<0.05)." (PMID 34351868, 2021).
Thyroid carcinoma (2 papers, 2021 to 2022). "Overall, we observed significant association between IGSF10 and immune checkpoint genes such as CD200R1, VSIR, CD160, CD28, BTLA, and CD40LG in several tumors including low-grade glioma (LGG) and thyroid carcinoma (THCA)." (PMID 34351868, 2021).
acute myeloid leukemia (1 paper, 2022). Acute myeloid leukemia (AML) is a group of neoplasms arising from precursor cells committed to the myeloid cell-line differentiation. "IGSF10 was expressed differently in 33 tumor tissues, with the highest expression in Acute myeloid leukemia (LAML)." (PMID 36685968, 2022).
breast tumors (1 paper, 2015). "Interestingly, some of the negative regulators of activin signaling pathway such as follistatin, β-glycan, IGSF1, and IGSF10 showed downregulation in breast tumors compared with normal samples." (PMID 28721365, 2015).
calcific aortic valve disease (1 paper, 2023). "IGSF10, a pro-inflammatory cytokine, is down-regulated in calcific aortic valve disease." (PMID 37662558, 2023).
cleidocranial dysplasia (1 paper, 2025). "Moreover, IGSF10 mutations have also been viewed as key contributors to other developmental diseases, including combined pituitary hormone deficiencies (CPHD), cleidocranial dysplasia (CCD), and Kallmann syndrome (KS)." (PMID 41447338, 2025).
diffuse large B-cell lymphoma (1 paper, 2022). "In contrast, IGSF10 had higher expression levels in tumors relative to normal samples in Lymphoid neoplasm diffuse large B-cell lymphoma (DLBC), Glioblastoma multiforme (GBM), LAML, Brain lower grade glioma (LGG), PAAD and Thymoma (THYM)." (PMID 36685968, 2022).
hypogonadism (1 paper, 2016). A disorder characterized by decreased function of the gonads. "Two patients (out of 14 patients from this HH cohort with functional hypogonadism) were identified as heterozygous for a shared loss‐of‐function mutation in IGSF10 (NM_178822: c.7353_7354insATCA: (rs570110855) p.L2452 fs)." (PMID 27137492, 2016).
Kallmann syndrome (1 paper, 2016). Kallmann syndrome (KS) is a developmental genetic disorder characterized by the association of congenital hypogonadotropic hypogonadism (CHH) due to gonadotropin-releasing hormone (GnRH) deficiency, and anosmia or hyposmia (with hypoplasia or aplasia of the olfactory bulbs). "To explore the possible role of mutations in IGSF10 in conditions of GnRH deficiency, we carried out targeted exome sequencing of IGSF10 in an adult cohort of 334 patients with HH due to Kallmann syndrome, idiopathic HH, or functional hypogonadism (hypothalamic amenorrhea (HA) or HA equivalent)." (PMID 27137492, 2016).
paraganglioma (1 paper, 2022). A benign or malignant neoplasm arising from paraganglia located along the sympathetic or parasympathetic nerves. "However, there was no notable change in the expression level of IGSF10 between CHOL, Pheochromocytoma and paraganglioma (PCPG), Uterine carcinosarcoma (UCS), and non-tumor tissues." (PMID 36685968, 2022).
sarcopenia (1 paper, 2025). Progressive decline in muscle mass due to aging which results in decreased functional capacity of muscles. "Five key CGs—NOX4, STC2, NEK6, IGSF10, and EMX2—were identified as molecular links between SSc and sarcopenia." (PMID 40977679, 2025).
triple-negative breast carcinoma (1 paper, 2020). An invasive breast carcinoma which is negative for expression of estrogen receptor (ER), progesterone receptor (PR), and human epidermal growth factor receptor 2 (HER2). "Decreased levels of the IGSF10 mRNA were observed in luminal, HER2-positive, and triple-negative breast cancer samples compared with normal samples." (PMID 33150070, 2020).
viral infection (1 paper, 2025). "Pursuing this, exogenous IGSF10 was stably expressed in human LUAD cell line A549 and H1299 by viral infection to determine the impact of IGSF10 on LUAD cells in vitro." (PMID 41447338, 2025).
cancer (9 papers, 2020 to 2025). A tumor composed of atypical neoplastic, often pleomorphic cells that invade other tissues. "In summary, these findings indicate that low expression of IGSF10 is significantly associated with the incidence of cancer in LUAD patients and that LUAD cells have a stronger tumorigenesis ability (p < 0.001)." (PMID 41447338, 2025). "The outcomes confirmed that IGSF10 was noticeably positively associated with MMR genes in 27 kinds of cancers, besides CHOL, MESO, OV, STAD and TGCT." (PMID 36685968, 2022). "According to our findings, the level of IGSF10 is associated with cancer immunity, providing a new idea for individualized cancer immunotherapy, and is expected to be a potential immunological and prognostic biomarker." (PMID 36685968, 2022). "The outcomes of the heatmap showed that nearly all immune-related genes have been positively associated with IGSF10 in the vast majority of cancers." (PMID 36685968, 2022). "Over the past few years, growing proofs have also validated the definitive role of IGSF10 as a prominent biomarker in a variety of cancers, including osteosarcoma, endometrial cancer, oral tumour, and multitype breast cancers." (PMID 41447338, 2025). "A systematic pan‐cancer analysis using multiple bioinformatics ways has shown differential expression of IGSF10 in normal and tumour tissues, indicating the prognostic value of IGSF10 in human pan‐cancer." (PMID 41447338, 2025). "The expression of proteins in cancer tissue and adjacent tissue was analysed using the cProSite database, and the results showed that IGSF10 was significantly underexpressed in HNSC, LUAD, and LUSC, while the opposite was true in LIHC." (PMID 41447338, 2025). "To understand the prognostic value of IGSF10 in a vary of cancers, we investigated correlations between IGSF10 expression and OS of tumor sufferers by single variate Cox regression analysis." (PMID 36685968, 2022). "Our outcomes suggested that IGSF10 expression performed a detrimental function in six kinds of cancer including BLCA, CESC, SARC, STAD, THCA, and UCEC." (PMID 36685968, 2022). "We obtained expression data of IGSF10 in various cancers from multiple friendly public databases open to the world, which was helpful to discover variations in IGSF10 expression in a vary of cancers." (PMID 36685968, 2022). "In most cancer types, IGSF10 expression was strongly related to immune cells infiltration, immune checkpoints, immune modulators, TMB, MSI, MMR, and DNA methyltransferases, among others." (PMID 36685968, 2022). "The expression of IGSF10 was highly positively related to these four DNA methyltransferases in 24 cancers, except CHOL, KICH, MESO, OV, PCPG, STAD, TGCT, and UCS." (PMID 36685968, 2022). "Our findings indicated that IGSF10 expression were notably different between tumor and normal tissues across multiple cancer types." (PMID 36685968, 2022). "In summary, our systemic pan-cancer analysis showed for the first time aberrant IGSF10 expression across different tumors." (PMID 36685968, 2022). "The IGSF10 expression was noticeably positively correlated with these four DNA methyltransferases in 24 cancers, except CHOL, KICH, MESO, OV, PCPG, STAD, TGCT, and UCS." (PMID 36685968, 2022). "In this study, we found that IGSF10 has different degrees of SNVs and CNVs in most cancer types, among which IGSF10 is most prone to SNVs in SKCM and UCEC." (PMID 36685968, 2022). "Bubble plot confirmed that CNV of IGSF10 was positively related to mRNA expression in eight cancers, including CESC, BLCA, OV, UCS, ACC, HNSC, LUSC, and ESCA." (PMID 36685968, 2022). "Survival analysis showed that IGSF10 expression correlated with overall survival of patients belonging to 6 cancer types, namely, KICH, SARC, LGG, UCEC, THYM, and LUAD." (PMID 34351868, 2021). "Overall, we observed significant correlation between IGSF10 expression and immunoscores in several cancer types (R=0.266, P=2.98e-19)." (PMID 34351868, 2021).
cancer (continued). "In addition, we analysed the differential expression of the IGSF10 gene in cancer tissue and adjacent tissue of the same patient to determine that IGSF10 was significantly underexpressed in cancer tissue." (PMID 41447338, 2025). "Notably, we also innovatively proposed that IGSF10 exerts a potential effect on ferroptosis, a hot topic that functions in a variety of diseases, especially cancer therapy." (PMID 41447338, 2025). "Nowadays, the correlation between IGSF10 and cancers is becoming increasingly attractive." (PMID 41447338, 2025). "As a prognostic marker across various cancers, further research on IGSF10 is essential and may uncover additional therapeutic avenues." (PMID 40598621, 2025). "To date, few studies have reported on relationships between IGSF10 gene variations and cancers." (PMID 36685968, 2022). "IGSF10 expression in tumor samples correlates with prognosis in most cancers." (PMID 36685968, 2022). "Gene enrichment analysis revealed that IGSF10 may have an effect on the occurrence, progression or immunity of cancer via participating in lymphocyte differentiation and cell molecules adhesion." (PMID 36685968, 2022). "The KEGG results further suggested that IGSF10 could adjust the occurrence and development of cancers via participating in the “cell molecules adhesion” signaling pathway." (PMID 36685968, 2022). "Although researchers have conducted multiple studies on IGSF10, until now, the role of IGSF10 in most cancers has remained largely unknown." (PMID 36685968, 2022). "These outcomes propose that aberrant IGSF10 expression may play a critical function in tumorigenesis by regulating DNA methylation in cancers." (PMID 36685968, 2022). "Methylation of IGSF10 in a vary of cancers was analyzed via the usage of GSCA database." (PMID 36685968, 2022). "We aimed to analyze the immunological and prognostic value of IGSF10 in pan-cancer." (PMID 36685968, 2022). "These consequences suggest that IGSF10 may affect tumorigenesis and development by means of regulating DNA repair and DNA methylation in cancers." (PMID 36685968, 2022). "Finally, we integrated RNA-seq information to analyze the IGSF10 expression in a vary of cancer and normal samples." (PMID 36685968, 2022). "CNV pie plot represented the proportion of different types of CNV of IGSF10 gene in each cancer." (PMID 36685968, 2022). "Furthermore, we found that IGSF10 can serve as a valuable prognostic biomarker for certain types of cancer." (PMID 36685968, 2022). "Likewise, we investigated the impact of CNV of IGSF10 on the prognosis of patients with various cancers." (PMID 36685968, 2022). "Therefore, we investigated the correlations between IGSF10 expression and immune cell infiltration in a vary of cancers via the usage of the TIMER online database." (PMID 36685968, 2022). "The expression of IGSF10 was significantly reduced in most cancer types." (PMID 34351868, 2021). "We then analyzed expression levels of IGSF10 in TCGA pan-cancer datasets." (PMID 34351868, 2021). "Interestingly, IGSF10 expression was positively correlated with several cancer-related biological processes, including DNA repair (HALLMARK_DNA_REPAIR), cell cycle (HALLMARK_G2M_CKECKPOINT), and glycolysis (HALLMARK_GLYCOLYSIS) pathways in both datasets." (PMID 33150070, 2020). "However, the function of IGSF10 in pan-cancer stays unclear." (PMID 36685968, 2022). "Our findings confirmed that excessive IGSF10 expression was correlated with terrible PFI of cancer sufferers in BLCA, COAD and KICH, while low IGSF10 expression was correlated with bad PFI of cancer sufferers in BRCA, LUAD, LUSC, and TGCT." (PMID 36685968, 2022). "We observed notably correlations between IGSF10 expression and infiltration levels of CD8+ T cells, CD4+ T cells, neutrophils, myeloid dendritic cells, macrophages and B cells in most cancer types." (PMID 36685968, 2022).
cancer (continued). "In the present study, using Stitch EMBL, the interaction network analysis revealed that a coordination of candidate proteins (FKBP4, ESRRA, IGSF10 and ABCB5) was involved in KEGG pathways of many cancers." (PMID 36517562, 2022). "FNBP1, FRMD3, IGSF10, IL11RA, and TOX2 have known roles in cancer." (PMID 38398114, 2024). "Furthermore, we additionally examined correlations between IGSF10 expression and DSS in a vary of cancers." (PMID 36685968, 2022). "Interestingly, from the heatmap, we can observe that nearly all immune checkpoint genes have been related to IGSF10 in most cancer types, with the exception of CESC, LUSC, MESO, SARC, UCEC, and UVM, majority of immune checkpoint genes have been positively related to IGSF10 in all kinds of tumors." (PMID 36685968, 2022). "However, the focus of IGSF10 is not on its prospective correlation with the immunological system, for example, B cells, CD4+/CD8+ T cells, neutrophils, macrophages, and dendritic cells, but on the close implications in some developmental diseases and various cancers." (PMID 41447338, 2025).
tumor (6 papers, 2020 to 2025). "To determine whether the enhanced tumour progression observed in IGSF10‐deficient cells is related to alterations in cell adhesion pathways, we examined the integrin β1/FAK pathway." (PMID 41447338, 2025). "Furthermore, we found that IGSF10 mutations were significantly correlated with prognosis of patients in multiple tumor types." (PMID 36685968, 2022). "In addition, IGSF10 expression was closely associated with age, tumor size, and TNM stage." (PMID 33150070, 2020). "We have demonstrated, from multiple dimensions, that IGSF10 plays a comprehensive tumour‐suppressive role in LUAD, and also plays a role in the ferroptosis‐related pathway ‘Response to iron ion’ (p < 0.01)." (PMID 41447338, 2025). "To study IGSF10 expression levels across various tumor stages, we used the UALCAN online tool to compare IGSF10 expression in tumor samples from patients at various tumor stages." (PMID 36685968, 2022). "These outcomes all confirmed that IGSF10 expression was closely correlated with the tumor-infiltrating immune cells, affected the prognosis of sufferers, and provided a novel target for the development of immunosuppressants." (PMID 36685968, 2022). "Bubble chart showed differences between IGSF10 gene methylation levels in various tumor and normal specimens." (PMID 36685968, 2022). "TIMER database analysis showed that IGSF10 expression positively correlated with the proportion of tumor-infiltrating B cells, CD4+ T cells, CD8+ T cells, neutrophils, macrophages, and dendritic cells in the TCGA-LUAD dataset." (PMID 34351868, 2021). "Our results showed that LUAD patients with high IGSF10 expression correlated with increased levels of tumor-infiltrating immune cells." (PMID 34351868, 2021). "In the TCGA-LUAD dataset, IGSF10 expression correlated positively with proportions of tumor-infiltrated B cells, CD4+ T cells, CD8+ T cells, neutrophils, macrophages, and dendritic cells." (PMID 34351868, 2021). "IGSF10 expression correlated with age (P < 0.001), tumor size (P = 0.003), and TNM stage (P = 0.03)." (PMID 33150070, 2020). "We analyzed the IGSF10 expression in different tumor tissues and normal tissues." (PMID 36685968, 2022). "Next, we analyzed IGSF10 expression in a range of tumor tissues from the TCGA database." (PMID 36685968, 2022). "IGSF10 expression was significantly correlated with age, tumor size, and tumor stage." (PMID 33150070, 2020). "Our research showed that IGSF10 may perform a specific function in regulating tumor immunity." (PMID 36685968, 2022). "Crucially, whether these genes influence tumor development through established pathways—FcεRI signaling (MS4A2), Integrin-β1/FAK (IGSF10), or ERK transduction (MFAP3L)—requires further validation, as does their relationship with MSC activity." (PMID 40598621, 2025). "Furthermore, tumor-infiltration levels of immune cells (B cells, CD4+ T cells, CD8+ T cells, neutrophils, macrophages, and dendritic cells) were significantly higher in patients with high IGSF10 expression compared to those with low IGSF10 expression." (PMID 34351868, 2021).
IGSF10 also shares sentences with these, for which no sentence is quoted: endometrial cancer (3 papers); cervical squamous cell carcinoma (2); colorectal cancer (2); head and neck squamous cell carcinoma (2); uterine corpus endometrial carcinoma (2); Adrenocortical carcinoma (1); Bladder urothelial carcinoma (1); Breast invasive carcinoma (1); cholangiocarcinoma (1); colon adenocarcinoma (1); endocervical adenocarcinoma (1); glioblastoma (1); Kidney chromophobe (1); low grade glioma (1); Lung squamous cell carcinoma (1); lymphoid neoplasm (1); melanoma (1); neuroblastoma (1); ovarian serous cystadenocarcinoma (1); Pan (1); pancreatic cancers (1); Pheochromocytoma and (1); Pituitary Hormone Deficiency (1); prostate adenocarcinoma (1); rectum adenocarcinoma (1); sarcoma (1); Skin cutaneous melanoma (1); testicular germ cell tumor (1); thymoma (1); uterine carcinosarcoma (1).